MIR491 (microRNA 491)
Synonyms: hsa-mir-491; MIRN491; mir-491
Gene: MicroRNA gene on chromosome 9 (20,716,105 to 20,716,188, forward strand). Ensembl gene ENSG00000207609.
Gene Ontology:
Biological process: miRNA-mediated post-transcriptional gene silencing
Cellular component: RISC complex
Homologues: Orthologues: chimpanzee ptr-mir-491 (100% identical), macaque mml-mir-491 (100% identical), dog MIR491 (99% identical), pig MIR491 (99% identical), mouse Mir491 (95% identical), guinea pig MIR491 (94% identical), rabbit MIR491 (65% identical).
Diseases named in the same sentence as MIR491 in open-access papers:
MIR491 is named in the same sentence as 2 diseases in open-access papers, as found by Europe PMC text mining. Sharing a sentence is not in itself a finding about the gene and the disease. The quoted sentences say what the papers report.
glioblastoma (1 paper, 2015). The most malignant astrocytic tumor (WHO grade IV). "Our study aimed to determine whether MIR-491 functions as a tumor suppressor gene in glioblastoma (GBM), by suppressing key cancer hallmarks through coordinate regulation of the predicted targets." (PMID 26682264, 2015).
tumor (1 paper, 2015). "Together, these studies demonstrate that MIR-491 is a major tumor suppressor that coordinates a wide range of targets to impact key hallmarks of tumorigenesis." (PMID 26682264, 2015).